CYP27B1 (cytochrome P450 family 27 subfamily B member 1)
Diseases named in the same sentence as CYP27B1 in open-access papers (continued):
Sharing a sentence is not in itself a finding about the gene and the disease.
hypophosphatemia (11 papers, 2013 to 2025). Lower than normal levels of phosphates in the circulating blood. "Central to diagnosis is recognizing hypophosphatemia with low or inappropriately normal 1,25 Vit D as a hallmark of TIO, reflecting FGF-23's suppression of CYP27B1 despite hypophosphatemia's stimulatory effect." (PMID 40951211, 2025). "It is characterized by increased circulating levels of FGF23, which leads to hypophosphatemia and suppression of vitamin D 1α-hydroxylase (Cyp27b1), resulting in decreased production of 1,25-dihydroxyvitamin D3 (1,25D)." (PMID 37490334, 2023). "A key diagnostic hallmark is hypophosphatemia accompanied by low or inappropriately normal 1,25-dihydroxyvitamin D (1,25 Vit D) levels, reflecting FGF-23's inhibition of renal 1-alpha-hydroxylase (CYP27B1) despite the stimulatory effects of low phosphate." (PMID 40951211, 2025). "Both hypophosphatemia and low FGF-23 levels increase Cyp27b1 and inhibit Cyp24a1 expressions and activities." (PMID 35414099, 2022). "Hyp mice lacking Cyp27b1 have normocalcemia and hypophosphatemia; analyses of entheses from these mice will show if absence of 1,25D action in Hyp mice will worsen the Hyp enthesopathy phenotype." (PMID 37490334, 2023).
asthma (10 papers, 2006 to 2025). "The haplotype analysis revealed that the ACTATGG haplotype (p = 0.032; OR = 2.84; 95% CI: 1.06–7.64) for BsmI, ApaI, TaqI, CYP27B1 (rs4646536), CYP27B1 (rs703842), CYP27B1 (rs3782130), CYP27B1 (rs10877012) was associated with a higher risk of asthma." (PMID 36839181, 2023). "To date, there are no studies determining that the CYP27B1 rs3782130 polymorphism influences the development of asthma." (PMID 36839181, 2023). "The observation that CYP27B1 is expressed in the lungs of both mice and human suggests that the association between low serum vitamin D levels and asthma in human is unlikely to be explained by conversion of 25(OH)D to 1,25(OH)2D." (PMID 25391140, 2014). "SNPs in the vitamin D pathway (CYP27A1, CYP27B1, CYP2R1, CYP24A1, and GC) affecting 25OHD levels demonstrated moderate effects on risk of asthma in a prior adult study, but the role of these variants on asthma risk later in life is unknown." (PMID 28486474, 2017). "Variants in CYP2R1, CYP27B1 and CYP24A1 or other genes in the metabolic pathway of vitamin D have not been tested so far with asthma or allergy but several of the VDR-controlled genes tested here already have been associated with asthma and allergy." (PMID 16600026, 2006).
lung carcinoma (10 papers, 2011 to 2024). "When the data were analyzed in subgroups of subjects stratified by smoking status, we found that smokers with variant homozygous rs3782130 in CYP27B1 had significantly increased risk of lung cancer (OR=1.91; 95% CI: 1.04-3.53)." (PMID 25544771, 2015). "Moreover, in contrast to lung cancer cells, CYP27B1 expression in alveolar macrophages from lung cancer patients showed positive association with cancer progression." (PMID 29657326, 2018). "This conclusion can aid better personalized medicine for lung cancer management, while further assessment for genetic variants of CYP3A4, CYP27B1, CYP24A1, GC, and VDR is still required to address more robust evidence." (PMID 38482381, 2024). "We genotyped 296 SNPs in CYP2R1, CYP27A1, CYP27B1, CYP24A1, and VDR and observed associations between 27 SNPs and lung cancer status after the adjustment for age, gender, and race, all of which had passed the Hardy–Weinberg equilibrium assessment." (PMID 29726119, 2018). "We identified 25D3 status as a novel host factor that influences the growth of EGFR mutant lung cancer and discovered that 25D3 signaling persists despite dramatic reduction in CYP27B1 expression and 1αOHase activity." (PMID 26654942, 2016). "In this study, we found CYP27B1 expression was lower in lung cancer than in normal tissues, and the patients with high CYP27B1 expression had better survival outcome, especially in old patients." (PMID 25544771, 2015). "Increased expression of CYP27B1 has been reported in alveolar macrophages of lung cancer patients, with the highest expression being found in more advanced disease stages." (PMID 25544771, 2015). "Some studies have associated greater expression of the CYP27B1 gene, as well as greater histological differentiation of the tumor, with an increase in OS in patients diagnosed with lung cancer; however, this mechanism is not entirely clear." (PMID 37627104, 2023). "The implication of our findings is that dietary vitamin D3 supplementation may be used as a safe and effective approach to increase 25D3 levels and slow the growth of EGFR mutant lung cancer, even in tumors that express CYP27B1 at low levels." (PMID 26654942, 2016). "CYP27B1-expressing EGFR mutant lung cancer cells (HCC827) are able to produce 1,25D3 from 25D3." (PMID 26654942, 2016). "Our study showed that CYP27B1 expression in lung cancer was different by the rs3782130 genotype." (PMID 25544771, 2015). "Determining whether 1αOHase is required for 25D3-mediated activity advances the clinical potential of dietary vitamin D3 supplementation because CYP27B1 expression is significantly decreased in EGFR mutant lung cancer cells under pressure of erlotinib treatment both in vitro and in vivo." (PMID 26654942, 2016). "We further genotyped 296 SNPs in the same subjects (N = 761) in CYP2R1, CYP27A1, CYP27B1, CYP24A1, and VDR genes directly involved in vitamin D metabolism, with an objective to elucidate variants that may modulate vitamin D levels, thereby potentially explaining their associations with lung cancer." (PMID 29726119, 2018). "Moreover, it has been shown that expression of the CYP24A1, CYP27B1, and VDR genes in lung cancer is affected by tumor differentiation and characterization." (PMID 36986255, 2023). "Thus far, we know that the genetic expression of CYP24A1, CYP27B1, and VDR in lung cancer is affected by tumor differentiation and characterization." (PMID 34836039, 2021). "However, we and others find that CYP27B1 mRNA expression is highly variable across NSCLC cell lines and resected human lung cancers." (PMID 26654942, 2016). "Our meta-analysis revealed the lack of association of CYP2R1 (rs10741657), CYP27B1 (rs3782130), CYP27B1 (rs10877012), CYP24A1 (rs6068816), CYP24A1 (rs4809960), CYP3A5 (rs776746), GC (rs7041), GC (rs4588), and VDR (ApaI: rs7975232) with lung cancer." (PMID 38482381, 2024).
Obesity (10 papers, 2013 to 2025). Accumulation of substantial excess body fat. "The dominant model revealed a higher risk of COPD in patients with obesity (p = 0.014), overweight (p = 0.012), smokers (p = 0.024), former smokers (p < 0.001) and in carriers of the CYP27B1 rs4646536-AA genotype (p = 0.008)." (PMID 39583968, 2024). "In consistency with these results, in the recessive model, obesity (p = 0.016), overweight (p = 0.013), smokers (p = 0.014), former smokers (p < 0.001), and CYP27B1 rs4646536-A allele carriers (p = 0.013) were associated with a higher COPD risk." (PMID 39583968, 2024). "Our present study clearly indicates that hypermethylation of specific sites in the CYP2R1 and CYP27B1 genes might regulate gene expression with special reference to the risk of obesity and vitamin D metabolism." (PMID 37184736, 2023). "Consequently, epigenetic alterations such as hypermethylation in CYP2R1 and CYP27B1 genes are reported to interfere in the metabolic pathway and decrease vitamin D levels, thereby contributing to genesis of obesity-linked diseases." (PMID 37184736, 2023). "This is an important implication that CYP2R1 and CYP27B1 are crucial role players of vitamin D metabolism and pathophysiological mechanisms of obesity." (PMID 37184736, 2023). "The objective of this study was to determine the association between obesity and methylation of vitamin D-dependent genes (i.e., CYP2R1 and CYP27B1)." (PMID 37184736, 2023). "Some studies have found relationships between VDR polymorphisms and BMI, adiposity markers, or obesity and other research has found a relationship between BMI and polymorphisms of VDBP and CYP27b1." (PMID 35631190, 2022). "Only a few studies have focused on the genes involved in activation, catabolism and transport of 25OHD of which there has been only one study on activation gene CYP27B1 in relation to obesity." (PMID 33553043, 2020). "We found that obesity was associated with increased VDR mRNA levels in adipose tissues, while in the case of CYP27B1, an opposite trend was observed." (PMID 31652924, 2019). "In this study, we aimed to evaluate if obesity influences the expression of genes crucial for VD activation (CYP27B1), inactivation (CYP24A1) and action (VDR) in different adipose tissues depots." (PMID 31652924, 2019). "It was also demonstratedthat CYP27B1 knockout mice presented lower leptin levels and consumedsignificantly more food than their wild type counterparts, and targeted expression of human vitaminD receptor in adipocytes reduced lipolysis, fatty acid beta-oxidation andinduced obesity in mice." (PMID 41337665, 2025). "The genotypic model confirmed a higher risk of COPD in patients with obesity (p = 0.017), overweight (p = 0.015), smokers (p = 0.016), former smokers (p < 0.001), and carriers of the CYP2R1 rs10741657-AA genotypes (p = 0.028) and CYP27B1 rs4646536-AA (p = 0.004)." (PMID 39583968, 2024). "Gene-specific hypermethylation in the CYP2R1, CYP27B1, and VDR genes was observed in the obesity-induced mice." (PMID 37184736, 2023). "In obesity and vitamin D metabolism-related gene networks, vitamin D receptor (VDR), cytochrome P450 gene family, i.e., CYP2R1, CYP24A1, and CYP27B1, are key players in vitamin D metabolism and interconnected with energy balance, adipocyte physiology, and adipokine secretion." (PMID 37184736, 2023). "In adipose tissue, CYP27B1 level is lower in obese than lean women, whereas CYP24A1 expression does not differ between them explaining obesity associated VD3 deficiency." (PMID 33095902, 2021). "Studies on CYP27B1, CYP24A1 and GC genes demonstrated a lack of association with obesity and T2D in Europeans; however, significant associations with T2D were found in South Asians." (PMID 33553043, 2020).
sarcoidosis (10 papers, 2013 to 2025). Sarcoidosis is a multisystemic disorder of unknown cause characterized by the formation of immune granulomas in involved organs. "Likewise, we also verified the over-expression of several other inflammation-associated genes including CCL19, CXCL13, and CYP27B1 in the lung of both TB and sarcoidosis patients." (PMID 33097805, 2020). "Among 20 similar signature genes shared by TB and sarcoidosis identified through RNA-Seq analysis, we further confirmed similar over-expression of MMP12, ADAMDEC1, CCL19, CXCL13, and CYP27B1 in TB and sarcoidosis lungs." (PMID 33097805, 2020). "The observation of increased CYP27B1 mRNA in both TB and sarcoidosis lungs is consistent with clinical findings that 1,25(OH)2D3 is commonly over-produced in individuals with granulomatous inflammation, including both TB and sarcoidosis patients." (PMID 33097805, 2020).
colitis (9 papers, 2015 to 2025). Inflammation of the colon. "This study also showed that intestinal inflammation elevated the expression of the local CYP27B1 gene that encodes the 1α-hydroxylase, consistent with the findings in other experimental colitis models and human IBD patients." (PMID 39273035, 2024). "Cyp27b1-/- mice with 1,25(OH)2D3 deficiency is another colitis-prone strain that develops colonic inflammation at the age of 8-10 month." (PMID 36685588, 2022). "Previously reported rodents with increased susceptibility to DSS colitis have included vitamin D receptor- and Cyp27B1- KO mice." (PMID 30065252, 2018). "A previous study has shown that Cyp27b1-/- mice were more susceptible to DSS-induced colitis with increased IL-1 and IL-17 cytokines." (PMID 26790152, 2016). "E-cadherin in epithelial and immune cells was found to be expressed less in CYP27B1 knockout mice compared to their wild type counterparts in this DSS-induced colitis study." (PMID 32422882, 2020). "In the first known DSS-induced colitis mice study using gene therapy, CD11b+/Gr1+ monocytes were used as the cell vehicle as well as the macrophage-specific promoter (Mac1) to deliver and upregulate CYP27B1 expression in the colon to treat colitis." (PMID 32422882, 2020). "The increased susceptibilities of Cyp27B1 KO and VDR KO mice to colitis were shown to be caused in part by shifts in the composition of the gut microbiota in mice." (PMID 29599772, 2018). "Sequencing of fecal DNA from Cyp27B1 KO and VDR KO mice showed increased frequencies of Proteobacteria and colitis causing Helicobacteraceae family members." (PMID 29599772, 2018). "In those with colitis, the ratio of CYP27B1 to CYP24A1 may prove to be important for successful treatment." (PMID 32422882, 2020). "Cyp27B1 knockout (KO) and VDR KO mice were extremely susceptible to colitis." (PMID 29599772, 2018). "Those mice that were Cyp27b1 (−/−) showed decreased IL-10 in the proximal colon and Toll-like receptors 2 and 4 in the distal colon as well as decreased levels of circulating 1,25(OH)2VitD, thus implicating vitamin D affecting colitis in DSS‐treated mice." (PMID 27417766, 2015). "Interestingly, while cyp27b1 expression was increased in the kidney, an inverse pattern was observed in the colon, where animals in the colitis vehicle group exhibited elevated colonic cyp27b1, and this expression was reduced by probiotic and/or vitamin D treatment." (PMID 40944110, 2025). "Therefore, the elevated colonic cyp27b1 in untreated colitis may represent an attempt to control bacterial infiltration, while its reduction by probiotic and/or vitamin D may indicate decreased immune activation due to improved barrier integrity and reduced inflammation." (PMID 40944110, 2025). "Together with vitamin D and its proposed anti-inflammatory properties, vitamin D may reduce colitis by regulating COX-2, TNF-α, NF-κB through IkBa expression, RXR signaling, and vitamin D-activating enzymes CYP24A1 and CYP27B1." (PMID 32422882, 2020). "Neither liver CYP2R1 nor kidney CYP27B1 mRNA levels changed significantly with the induction of colitis." (PMID 30065252, 2018). "The severity of colitis was significantly higher in VDR and CYP27B1 knockout mice." (PMID 26130323, 2016).
prostate carcinoma (9 papers, 2011 to 2024). A carcinoma that arises from epithelial cells of the prostate gland. "Six studies reported the effects of CYP27B1 polymorphisms in prostate cancer, two reported in non-small cell lung cancer and one in digestive system tumor." (PMID 31467173, 2019). "Variants in VDR, CYP24A1, and CYP27B1 were associated with progression to prostate cancer-specific mortality in a case-only study (n = 1,294)." (PMID 25488826, 2015). "Polymorphisms in the vitamin D metabolism-related genes CYP24A1 and CYP27B1 were reported to be associated with colon as well as prostate cancer risk, respectively." (PMID 22576141, 2012). "A Chip assay generated data revelled the binding of EGF/EGFR complex to the promoter of CYP27B1 in PZ‐HPV7 cells which leads to prostate cancer development." (PMID 39434198, 2024). "Inhibitors of methylation in prostate cancer cell lines increased CYP27B1 expression supporting the importance of epigenetic marking of CYP27B1 in autocrine calcitriol synthesis." (PMID 33291213, 2020). "Reduced CYP27B1 gene expression level has been found in various tumors, including prostate cancer, non-small cell lung cancer." (PMID 31467173, 2019). "They found that normal prostate cells exhibited the highest expression of CYP27B1 among the tissues examined, while its expression was decreased in the following order: normal prostate, benign prostatic hyperplasia, and finally prostate cancer and its cell lines." (PMID 29899561, 2018). "Prostate cancer cells (LNCaP and 22Rv1) showed low to no expression of CYP27B1 (encoding a vitamin D 25-hydroxylase) and were unable to metabolize 25D to the active hormone 1,25D, as shown by the lack of CYP24A1 (encoding vitamin D 24-hydroxylase) induction by 25D." (PMID 36875158, 2023).
multiple sclerosis (8 papers, 2012 to 2025). A progressive autoimmune disorder affecting the central nervous system resulting in demyelination. "The study of the three different polymorphisms (rs118204009, rs118204011, and rs118204012) occurring within CYP27B1 in patients with multiple sclerosis showed that all were carriers of wild alleles and none of the rare variants were found." (PMID 32197412, 2020). "The important role of vitamin D in the ethiopathogenesis of multiple sclerosis and vitamin-D-dependent rickets type 1 was based on CYP27B1 polymorphisms." (PMID 32197412, 2020). "This study concluded that a rare variant (rs118204011) in the CYP27B1 gene affects vitamin D activity and may increase susceptibility to developing multiple sclerosis." (PMID 41150797, 2025). "Consistently, the CC genotype of CYP27B1 is associated with poor response to interferon-α-based treatment of chronic hepatitis C in the present and in our previous study, as well as with the risk of bone disease or autoimmune disorders such as multiple sclerosis or type 1 diabetes." (PMID 22808108, 2012). "For instance, VitD deficiency has been linked to an increased risk of multiple sclerosis, and genetic polymorphisms in CYP2R1 and CYP27B1 have been associated with multiple sclerosis severity." (PMID 40152347, 2025). "Furthermore, while differences in CYP27B1 and VDR expression have been documented in autoimmune and chronic inflammatory diseases such as multiple sclerosis and cancer, direct transcriptomic evidence in RA remains scarce." (PMID 40870018, 2025).
vitamin D-dependent rickets, type 1A (8 papers, 2015 to 2025). "Vitamin D-dependent rickets type 1A is a rare autosomal recessive disorder caused by pathogenic variants in the CYP27B1 gene." (PMID 41574189, 2025). "Two novel CYP27B1 variants were identified, expanding the known mutation spectrum of vitamin D-dependent rickets type 1A." (PMID 40218268, 2025). "Vitamin D-dependent rickets type 1A is caused by pathogenic variants of CYP27B1 gene, which is inherited in autosomal recessive pattern." (PMID 39351120, 2024). "Pathogenic variants of the CYP27B1 gene can lead to 1α-hydroxylase deficiency; the disorder is commonly known as vitamin D-dependent rickets type 1A (VDDR 1A) or pseudo-vitamin D deficiency rickets type 1A." (PMID 39351120, 2024). "Vitamin D-dependant rickets type 1A (VDDR1A) is a rare autosomal recessive disorder caused by pathogenic variants in the CYP27B1 gene." (PMID 35600579, 2022).